TNF (tumor necrosis factor)
Diseases named in the same sentence as TNF in open-access papers (continued):
Sharing a sentence is not in itself a finding about the gene and the disease.
cancer (continued). "Consequently, targeting YAP/TEAD transcriptional activity could be a promising new way to inhibit pathological effect induced by TNF, and probably by other cytokines, on cell phenotype in human inflammatory-associated diseases such as cancer and chronic inflammatory disorders." (PMID 35401557, 2022). "TNF-α is a major mediator of inflammation and is involved in cancer initiation, progression, invasion, and metastasis." (PMID 36139553, 2022). "The most common and promising approach is stimulating the death receptors and the use of death ligands such as TRAIL and TNFα to induce apoptosis in cancer cells." (PMID 36358282, 2022). "It has been shown that cancer cells release TNF-α, promoting cell transformation, tumorigenesis, and metastasis." (PMID 35207722, 2022). "TNF was named due to its early promise as a powerful anticancer cytokine, but its role in cancer became quite paradoxical in subsequent research." (PMID 35844550, 2022). "Through the generation of tumor necrosis factor-alpha (TNF-α), chronic inflammation promotes the transition of epithelial cells into cancer cells." (PMID 35159669, 2022). "There is a strong rationale to develop small molecular compounds that mimic LPS or TNFα signaling to treat cancer in combination with an IAP antagonist while avoiding the serious side effects from LPS or TNFα." (PMID 36119107, 2022). "This is consistent with our recent report that SM-164 is the strongest IAP antagonist to induce cancer cell apoptosis in the presence of TNFα." (PMID 36119107, 2022). "Previous studies have indicated that TNF-α usually activates the typical NF-κB signal pathway in cancers." (PMID 35418179, 2022). "NF-κB p65-induced COP9 signalosome 5 (CSN5) is essential for maintaining TNF-α-induced stability of PD-L1 in cancer cells." (PMID 35279217, 2022). "Proinflammatory cytokines, TNF-α and IL-6, mediate the augmented muscle protein degradation in cancer." (PMID 35736478, 2022). "The research journey into the role of TNF in immunology in general and cancer immunology in particular started with huge expectations." (PMID 36358688, 2022). "Decades later, thalidomide was discovered to have anti-inflammatory and anti-cancer effects, mainly via decreasing tumor necrosis factor (TNF)-alpha and its anti-angiogenetic property." (PMID 36611747, 2022). "Endothelial cell-generated TNF-α then triggers CXCL1/2 expression by cancer cells, which subsequently recruits CD11b+Gr1+ myeloid-derived suppressor cells that express CXCR2 (the receptor for CXCL1/2)." (PMID 36241629, 2022). "TNF-α is known as a multifunctional cytokine that contributes to cancer development and also participates in different signaling pathways connected to inflammation, proliferation, survival, invasion, and migration in BC." (PMID 36226048, 2022). "During cancer cachexia, cytokines such as TNF‐α and IL‐6 enter the central nervous system and promote the wasting of surrounding tissues, such as muscles through the hypothalamus–pituitary–adrenal and hypothalamus–pituitary–gonad axes." (PMID 36105371, 2022). "Apoptotic/necrotic death induced by Smac mimetics and TNF-α crucially depends on RIPK1 because RIPK1 deficient MEFs, and cancer cells in which RIPK1 is depleted, are resistant to TNFR1 killing following treatment with Smac mimetics." (PMID 35406442, 2022). "Phase I and II clinical trials using the TNF-α antibodies infliximab or etanercept for the treatment of advanced cancer revealed 20% disease stabilization or better response." (PMID 35844550, 2022). "One of the first systemic inflammatory molecules identified in cancer patients is tumor necrosis factor alpha (TNF-α), initially termed “cachectin”." (PMID 35441960, 2022).
cancer (continued). "We also expanded our investigation to physiological NETs-inducers: IL-8 a key mediator associated with inflammation; TNF-α is a prominent inflammatory cytokines involved in various auto-inflammatory conditions; and TGF-β activates neutrophils in cancer." (PMID 36506529, 2022). "• Inflammatory cytokines released by cancer cells.• Since stimulation by IL-6 and TNF-α induces bone-resorbing multinucleated giant cells, it is possible that some mechanisms of the bone-resorptive effects of IL-6 are not mediated by the RANK/RANKL pathway." (PMID 36626519, 2022). "The increase of TNF, IL-1β, and IL-10 secretion in healthy colonocytes (V BM alone and with hPA120 treatments; p < 0.05) and for TNF and IL-10 in cancer cells (treatments except O BM + hPA120 and V BM, respectively; p > 0.05) were stated." (PMID 36296918, 2022). "TNF-α plays pivotal roles in autocrine and paracrine signaling mechanisms that activate pathways important in invasive and chemoresistant cancer cell behaviors." (PMID 35326569, 2022). "Genes belonging to TNF and C1q were manually curated in order to better analyze domain content and evolution because of the role of these genes in immunity and cancer regulation." (PMID 35260071, 2022). "Calebin A inhibited TNF-α-induced NF-κB activation and IκBα degradation by suppressing DNA binding in cancer cells." (PMID 36185259, 2022). "Cancer cells often evade apoptotic response following TNFα stimulation by altering signaling cross-talks." (PMID 36240239, 2022). "Previous studies have shown that the serum level of TNF-α in cancer patients decreased significantly after chemotherapy." (PMID 36047064, 2022). "Other roles of TNF-α include the recruitment of Tregs at the cancer site and impairment of immune surveillance by suppressing T cell responses and the cytotoxic activity of activated macrophages." (PMID 35493517, 2022). "Another important molecule involved in the adherence and transmigration of cancer cells via the endothelium is E-selectin, which is induced by TNF-α." (PMID 35203510, 2022). "RNA sequencing revealed that the upregulated cancer-related genes were mainly enriched in several signaling pathways, including the TNF signaling pathway, NOD-like receptor signaling pathway, and NF-κB signaling pathway." (PMID 36578029, 2022). "The addition of TLR4 inhibitor markedly reduced LPS-induced production of TNFα by the cancer cells, suggesting that LPS-induced TNFα production by the cancer cells is TLR4 dependent." (PMID 36119107, 2022). "Here, we investigated the effect of Fx on the inflammatory factor TNF-α-induced heterogeneous adhesion of cancer cells MCF-7 to HUVECs." (PMID 36160416, 2022). "TNF-α produced by cancer cells is a cue to improve the ability of CAFs to model the extracellular matrix (ECM)." (PMID 35681719, 2022). "In general, TNFα levels were low in the culture medium because only a small number of cancer cells were cultured for a short term (overnight)." (PMID 36119107, 2022). "We identified 1948 peaks for E2F1 and 8282 peaks for p65 in HeLa cancer cells, prior and upon TNFα stimulation, respectively." (PMID 36291831, 2022). "A better strategy is instead to re-sensitize cells to TNF pro-apoptotic effect to clear more efficiently cancer cells or abnormal pro-inflammatory resident cells in inflammatory disorders, this strategy has been already proposed." (PMID 35401557, 2022). "Meanwhile, KEGG pathway analysis showed that pathways were significantly enriched including the relaxin signaling pathway, Toll-like receptor signaling pathway, TNF signaling pathway, IL-17 signaling pathway, and transcriptional misregulation in cancer." (PMID 35265129, 2022). "Resveratrol nanoparticles can inhibit the growth, proliferation and migration of cancer stem like cells by inducing M1-like macrophages producing inflammatory cytokines such as TNF-α, IL-6 and IL-1β." (PMID 36439106, 2022).
cancer (continued). "It has shown strong anti-proliferative and anti-metastatic effects in vitro and in vivo and also reduced the production of inflammatory cytokines such as IL-6 and TNF-α thus suggesting it to be an important therapeutic agent against cancer progression." (PMID 35081970, 2022). "Different pro-inflammatory markers, like TNF-α and IL-6, contribute to the pathogenesis of some organ damages and cancer." (PMID 36547085, 2022). "It was shown that yolkin activated the macrophages of BMDM cell line to produce and release innate immunity mediators, such as TNFα, type I Interferons and NO, which are important in the regulation of the immune response against pathogens or cancer cells." (PMID 35328547, 2022). "In cancer and inflammatory diseases, the major inflammasome is TNF-α, which activates the NF-κB pathway, whereas the minor inflammasomes are IL-1β, CCL2, and CCL5." (PMID 36139553, 2022). "Smac-mimetics LCL161 compound has been developed as an antagonist of the cellular inhibitor of apoptosis cIAP-1 and -2 and has been unsuccessfully evaluated in clinical trials for its ability of induce TNF-mediated apoptosis of cancer cells." (PMID 35251496, 2022). "The downregulated gene set in the TCGA dataset was significantly enriched in pathways associated with cancer, PI3K-AKT signaling pathway, TNF signaling pathway, and other related pathways." (PMID 36213837, 2022). "The results suggested that the risk score was more relevant to macrophage recruiting or monocyte recruiting regarding the anti-cancer immunity cycle, and more relevant to NFκB or TNFα pathways as regarding 11 cancer related pathways." (PMID 36248827, 2022). "Several studies have shown that members of the tumor necrosis factor (TNF) family play an important role in cancer immunoregulation, and trials targeting these molecules are already underway." (PMID 35000592, 2022). "It is known that IAP antagonist induction of cancer apoptosis is TNFα-dependent; in particular, the biological function of LPS largely depends on its stimulation of TNFα production." (PMID 36119107, 2022). "Previous studies focused on adults have found some associations between interleukin-6 (IL-6), interleukin-8 (Il-8), tumor necrosis factor α (TNFα) SNPs, and clinical outcomes in cancer patients." (PMID 35335997, 2022). "F2 cells maintained in culture also conserved the upregulation of genes associated with multiple signaling pathways (e.g. TNFα and PI3K-AKT signaling) associated with cancer cells." (PMID 35614362, 2022). "Analysis revealed the key genes were mainly enriched in the following pathways: cancer signaling pathway, TNF signaling pathway, PI3K-AKT signaling pathway, and HIF-1 signaling pathway." (PMID 35360660, 2022). "This went so far that the cloning of human TNF, which had been achieved and published in 1984, was examined in the general press around the globe, and its therapeutic potential in cancer treatment was hailed as the coming of a new era." (PMID 36358688, 2022). "Depending on the type of cancer, there is an upregulation in pro-inflammatory cytokines, e.g., TNF-α and IL-17, which are involved in tumorigenesis." (PMID 35054978, 2022). "Pro-inflammatory cytokines such as IL-1, IL-6, IL-17, and TNF-α promote proliferation and differentiation of cancer cells." (PMID 35252204, 2022). "TNF-α also plays a key role in regulating local and distal invasion, angiogenesis, and metastasis in numerous cancers, particularly in HGSOC." (PMID 35326569, 2022). "These genes were observed to be majorly associated with the cancer associated pathways such as MAP kinase, cytokine mediated inflammation, proinflammatory signaling cascade, TNF-induced apoptosis, T cell receptor stimulation and mitogenic pathways." (PMID 35672711, 2022).
cancer (continued). "have a potential pharmacological effect against RILI via the cancer pathways, TNF signaling pathway, and PI3K-Akt signaling pathway." (PMID 35360660, 2022). "TNF‐α accounts for 70–95% of biological activities and is based on the cytolysis of certain tumor cell lines, and was used as a potential anti-cancer therapy." (PMID 36550571, 2022). "ADAM17 is a member of ADAMs family, which mediates the shedding and maturity of various membrane proteins such as HB-EGF, TNFα, NOTCH, and cadherins and is implicated in cancer progression." (PMID 35138218, 2022). "HCV infection promotes IR through the insulin signaling pathway in hepatocytes and lead to a rise in levels of tumor necrosis factor and interleukin-6, which aid the advancement of liver steatosis and inflammation and subsequent cancer." (PMID 36115934, 2022). "Recently, another study demonstrated that TMEM100 functions as a cancer suppressor mainly by inhibiting the TNF signaling pathway in NSCLC 35, which is consistent with our results." (PMID 35371319, 2022). "These cells also serve as a primary source of TNF-α, which suppresses expression of the alarmin IL-33 in carcinoma cells." (PMID 36256464, 2022). "This bacteria was also shown to be more abundant in carcinoma patients and positively correlated with TNF-α production." (PMID 36090094, 2022). "Mechanistically, TNF-α, predominantly secreted by TAMs, decreases the expression of the alarmin IL-33 in carcinoma cells." (PMID 36256464, 2022). "For instance, treatment of PDA cells with recombinant TNF-α increased EGFR expression from carcinoma cells, while in another study recombinant TNF-α promoted the growth of Panc02 tumors in mice but inhibited KPC cell growth." (PMID 36256464, 2022). "It is important in TNF-α-induced inflammatory cascade and promotes the occurrence of chronic inflammation–induced cancer." (PMID 34047671, 2021). "CAF secretion of either exosome containing miRNA, Wnt proteins, Interleukin (IL)-1B, TNFα or fibrillar collagen can activate EMT of cancer cells." (PMID 34322664, 2021). "Vero cells infected for 24 h were compared with Vero cells infected for 12 h, and showed that the TNF signaling pathway and pathways in cancer are significantly enriched." (PMID 34202551, 2021). "Cancer-associated adipocytes secrete inflammatory cytokines such as interleukin (IL)-6 and tumor necrosis factor (TNF)-α, which are known to promote cancer progression by contributing to pro-cancer inflammation." (PMID 34071012, 2021). "Elevated levels of TNF-α are also seen in oral squamous cell carcinoma; this eventually leads to tumorigenicity of cancer cells." (PMID 33671607, 2021). "Functional enrichment analysis revealed that differentially methylated mRNAs, lncRNAs, and circRNAs were mostly enriched in transcriptional misregulation in cancer and TNF signaling pathway." (PMID 34868913, 2021). "The unique pathways of the patients aged ≥ 65 years ceRNA network included TGF-beta signaling pathway, TNF signaling pathway, and MicroRNAs in cancer." (PMID 33968126, 2021). "Inflammatory cytokines released by adipocyte, such as TNF-α, IL-6, are also able to affect cancer lipid metabolism with paracrine and endocrine activity, which will be discussed later." (PMID 34888248, 2021). "Such an activation of DCs by stimulatory signals including TNF-α increases CD8+ T cell-mediated antitumor immunity that is essential for the efficacy of cancer immunotherapy." (PMID 33919653, 2021). "In that regard, it has been suggested that CTX induces acute secretory activating phenotype (ASAP), producing CCL4, IL8, VEGF, and TNF-α from treated cancer cells, resulting in drastic changes in the tumour microenvironment." (PMID 33803675, 2021).
cancer (continued). "KEGG enrichment pathway analysis revealed that genes were significantly enriched in the TNF signaling pathway, metabolic pathways, osteoclast differentiation, protein digestion and absorption, and proteoglycans in cancer." (PMID 34466069, 2021). "As a pleiotropic molecule, a duality exists where TNF-alpha can promote proliferation or inhibit cellular growth in cancer cells." (PMID 35008824, 2021). "Next to other ROS, like superoxide, H2O2 is prone to induce cell death, for example through TNF- α signaling, in different cells, although its role in cancer development is ambivalent." (PMID 34671319, 2021). "Tumor necrosis factor (TNF) and its cancer promoting capacity, out of its role in proliferation, differentiation, and apoptosis, drew the experts’ attention." (PMID 34063545, 2021). "In contrast, gallic acid equivalent (GAE) treatment increased intracellular ROS production in human cancer colon fibroblast cells and decreased the expression levels of TNF-α, IL-1β, IL-6, and NF-κB to suppress cell proliferation." (PMID 33664749, 2021). "The uncovered mechanisms have translational potential, as we showed that T cell–derived TNF contributes to heart transplant rejection and synergizes with checkpoint blockade to result in clearance of an otherwise resistant murine cancer." (PMID 34752416, 2021). "Further studies in different cancer types are needed to define the clinical benefit of TNFα blockade in terms of dose and administration in patients undergoing anti-immune checkpoint treatment." (PMID 33540543, 2021). "Tumor Necrosis Factor (TNF) is an evolutionarily conserved pleiotropic cytokine, involved in host immune defense against pathogens and cancer." (PMID 35264975, 2021). "TNF-alpha has also been reported as an EMT-inducing cytokine in different cancer cell lines, including cells from colorectal origin, with and without the NF-κB-mediated upregulation of EMT transcription factors." (PMID 33654197, 2021). "The KEGG pathway enrichment analyses displayed that the potential targets were significantly enriched in Pathways in cancer, MicroRNAs in cancer, TNF signaling pathway, and Epithelial cell signaling in Helicobacter pylori infection, etc.." (PMID 33865425, 2021). "Distribution of TNF-α gene genotype among cachectic NSCL cancer patients considering the cachexia severity." (PMID 34900737, 2021). "NKp30 is another activating receptor on the NK cells responsible for eliminating cancer cells and inducing dendritic cells maturation by secretion of tumor necrosis factor-alpha (TNF-α), interferon-gamma (IFN-γ), perforins and granzymes." (PMID 34046039, 2021). "Macrophages, type I interferons, IFN-β, and TNFα can suppress cancer, while their impacts on tumorigenesis can be complex." (PMID 34945007, 2021). "A plethora of accumulated evidence highlights TNFα as a pro-tumoral cytokine, which stresses its appeal as a potential target to treat different cancers." (PMID 33540543, 2021). "In an even more compelling outcome, blockade of NF-κB activation is accompanied by sustained JNK activation and robust production of ROS in TNF-α-stimulated cancer cells." (PMID 34158609, 2021). "TNF-α belongs to a group of proinflammatory cytokines and is involved in cancer growth and progression." (PMID 33923108, 2021). "The detection limit has been experimentally demonstrated to be 10–15 M for TNF-α cancer marker, which is orders of magnitude higher than most label-free detection methods." (PMID 34138312, 2021). "Simultaneously, TNF can promote tumorigenesis and cancer progression by activating TNF receptor 2, which is expressed on immune cells and some cancer cells." (PMID 33578830, 2021). "Pro-inflammatory cytokines, including TNF-α, IL-1, IL-6, are usually increased in many types of cancer." (PMID 34944975, 2021).